NF1 (neurofibromin 1)
Diseases named in the same sentence as NF1 in open-access papers (continued):
Sharing a sentence is not in itself a finding about the gene and the disease.
tumor (continued). "One patient without NF-1 and tumor progression had an intralesional hemorrhage." (PMID 30619059, 2018). "The aim of the present study was to evaluate RNFL thickness in children with and without NF-1 who were diagnosed with OPG and to analyze the association of anatomical structural changes in tumor size and RNFL thickness with clinical changes in optic nerve function." (PMID 30619059, 2018). "Importantly, in all mouse models reported so far, including non-NF1-related tumor models, there was either no impact or a positive impact toward formation of benign tumors." (PMID 30479396, 2018). "Importantly, differential Etv5 and Etv5 network expression was not directly the result of Nf1 gene dysfunction in specific cell types, but rather reflects a property of the tumor as an aggregate tissue." (PMID 29787563, 2018). "The absence of NF1 in MPNSTs may lead to increased secretion of BMP2 that promotes malignant characteristics within the tumor microenvironment." (PMID 27494873, 2016). "While reduced expression or inactivation of other tumour suppressor genes, including PTEN, NF1, ATRX and DAXX, has been associated with specific GBM subtypes, we are not aware of any other wild type gene that behaves as a tumour suppressor in some GBM subtypes and as an oncogene in others." (PMID 27083054, 2016). "shRNA knockdown of four different MPNST cell lines revealed a significant reduction in tumour colony size growth, wound healing and cell invasion, thereby supporting a role for the increased expression of SPP1 in the malignant transformation and invasion of cells during NF1-MPNST development." (PMID 25884485, 2015). "However, the additional requirements for tumorigenesis indicate that complete loss of NF1 and hyperactivation of RAS in tumor progenitors is not sufficient for gliomagenesis and that cooperating molecular events must be at play." (PMID 26283963, 2015). "Furthermore, it was demonstrated that the silencing of the NF1 gene induces increased expression of vascular endothelial growth factor (VEGF), further clarifying the reasons of occurrence of a hypervascularized neoplasm, such as the GT." (PMID 25674553, 2015). "Morrison and colleagues (2008) studied the tumours of the peripheral nervous system (PNS) and demonstrated that the absence of Nf1-deficient neural crest stem cells in postnatal mice, supporting that the PNS tumours did not originate from these stem cells but rather from differentiated glia." (PMID 25708542, 2015). "It has been previously reported that an 18F-fluorodeoxyglucose (FDG) positron emission tomography/computed tomography (PET/CT) image with a T/L (Tumor/Liver) SUVmax ratio > 1.5 provides a high negative predictive value; however, it is not specific enough to make a NF1-related MPNST diagnosis." (PMID 26445379, 2015). "Clinically, our patient had no features of NF1 to support a tumor originating from the optic nerve." (PMID 24744944, 2014). "Dual color FISH analysis involving chromosome 17q showed that >10% of the cells from the tumor showed the deletion signal pattern of one red (NF1 region probe on 17q11) and two green [myeloperoxidase (MPO) gene region on 17q22 as the control probe), demonstrating a deletion of the NF1 gene." (PMID 24932270, 2014). "This study points towards a crucial role of Pten in nerve sheath tumour formation, however, the employed mouse model does not reflect the genetic nature of NF1 patients and the question why mice haploinsufficient for Pten and Nf1 completely lacked tumour development remains unsolved." (PMID 23139750, 2012). "Not all type 2 microdeletions can be PCR amplified by a primer set for common breakpoints, and thus we cannot rule out the involvement of NF1-REPs or the SUZ12 sequences in the deletion identified in tumor P004-7N, because MLPA results were consistent with this type of deletion." (PMID 21031597, 2011). "This tumor is seen in adults and has been described mostly in patients without a history of NF-1." (PMID 18823533, 2008).
tumor (continued). "In addition, we have assayed two other tumour-suppressor genes, WT1 and NF1, to see whether they play a role in colorectal carcinogenesis." (PMID 7947085, 1994). "A factor related to this type of tumor is that sometimes they develop from pre-existing plexiform neurofibromas being more than half of the cases, and sporadic appearances that are not related to NF1, represent about 40 % of cases, and 10 % originate in areas previously exposed to radiation." (PMID 40848702, 2025). "However, whether ECM plays a role in sustaining these NF1 mutant tumor proliferation and survival is not clear." (PMID 40025071, 2025). "As the specific impact of changes in tumor size on a possible change in VA has not been studied comprehensively, this is, to our knowledge, the first analysis evaluating the impact of calculated TGV as a potential risk factor for VA deterioration in NF-1-associated and sporadic OPG." (PMID 40643687, 2025). "These mutations may occur in receptors (e.g., KITKIT), effectors (BRAF, NRAS), or inhibitors (NF1, RASA2, CDKN2A, SPRED1) of the pathway, leading to proliferation of transformed melanocytes, abnormal differentiation, and persistent survival with impaired apoptosis of tumour cells." (PMID 41295253, 2025). "This is reflected in mice models, where systemic Sdhb heterozygosity is insufficient to induce tumour formation, Sdhb knock-out in medullary adrenal cells solely led to increased succinate levels in the absence of other PPGL hallmarks, but additional Nf1 mutations induced SDHx-like PPGLs." (PMID 39000369, 2024). "At the same time, loss of NF1, TSC1, or TβRII promoted the production of soluble inflammatory mediators such as IL6 and IDO1, which resulted in a non-cell-autonomous immune-suppressive tumor microenvironment that is characterized by increased LAG3+ CD8 and CD4 T cells." (PMID 38997291, 2024). "Surprisingly, the single tumor bearing NF1 A699Ifs*3 did not have a positive MPAS score, however, the allelic frequency of this variant was only 0.1, so loss of this TSG may have been insufficient to promote measurable MAP kinase pathway activation compared to oncogenic activators." (PMID 37369741, 2023). "Thus, NF1 might be required for spindle organization and chromosome segregation in circulating tumor-derived cells, as in neuron cells, rather than for the inactivation of the Ras protein." (PMID 36672653, 2023). "For his MTC tumor, despite the lack of previously reported MTC-related alterations, a de novo (acquired in embryo development, causing genetic mosaicism) frameshift mutation c.3338delT in the NF1 gene was detected with a VAF as high as 76.1%, strongly suggestive of a driver event." (PMID 36344509, 2022). "Therefore, finding a PPGL carrying somatic mutations in NF1 and ATRX may not be unexpected, and warns of the malignant potential of the tumour carrying the ATRX mutation." (PMID 36760809, 2022). "Moreover, the hypothesis of a co-occurring somatotroph tumor or hyperplasia has not been genetically ascertained in NF1 with GH excess." (PMID 35456261, 2022). "Our data further suggest that MBZ′s cytotoxic effect on NF1-related malignancies may result from a reduction in activated GTP-bound Ras and a subsequent decrease in pERK in MBZ-treated malignancies in vivo, thus directly targeting the molecular underpinnings for tumor development in this condition." (PMID 32650362, 2020).
tumor (continued). "Furthermore, CAPN1's ability to regulate NF1 and RAS may be utilized to suppress tumor development." (PMID 30131853, 2018). "Importantly, SCs lacking the Nf1 tumor suppressor evade ATP-mediated growth suppression." (PMID 30470263, 2018). "However, high-resolution studies have failed to provide any evidence for frequent NF1 alterations in de novo AML, although they suggested that NF1 mutations may contribute to tumour progression." (PMID 28637487, 2017). "To identify mechanisms that are commonly altered in Nf1- mediated tumorigenesis and might function as second events, we interrogated our tumor cell lines using a targeted expression array to compare expression of known PI3K pathway regulators and effectors amongst our tumor lines." (PMID 26000738, 2015). "In the context of neurofibromatosis type 1 (NF1), the absence of functional neurofibromin—an essential Ras GTPase-activating protein (GAP)—results in continuous Ras activation, contributing to tumor growth." (PMID 40725763, 2025). "Probably the most responsible for the prolonged misclassification of NF1 and NF2-SWN together was none other than Harvey Cushing who in 1917 stated that bilateral ‘nervus acusticus’ (VS) tumours were part of von Recklinghausen disease." (PMID 41160189, 2025). "A similar tendency of higher median tumor growth rates in patients with evidence of impaired VA without statistical significance could be shown in both subgroups of patients with and without NF-1 (NF-1 OPG: 0.137 vs 0.001 cm3/month, p = 0.16; non-NF-1 OPG: 0.036 vs 0.0003 cm3/month, p = 0.18)." (PMID 40643687, 2025). "Limitations of this case include the absence of tumor HPV/p16 testing and somatic NF1 profiling; these data would strengthen any mechanistic link between NF1 and penile SCC." (PMID 41245174, 2025). "Furthermore, lomitapide reduced tumor cell proliferation and significantly prolonged survival in at least one in vivo GBM model, suggesting that targeting lipid metabolism may represent a promising therapeutic strategy for both NF1-mutant and NF1 wild-type GBMs." (PMID 41294711, 2025). "While we have previously shown that the only proliferating (Ki67+) cells in the mouse Nf1-OPG are tumor cells, it is possible that we are not directly assessing tumor cell content." (PMID 41497446, 2025). "The anti-LAG3/PD-L1/Paclitaxel treatment showed the most significant metastasis reduction from tumors with NF1, TSC1, or TβRII inactivation but not from the 4T1-C1 control tumor." (PMID 38997291, 2024). "We found that the protein expression of NF1, TSC1, and TβRII, but not NF2 and PTEN was downregulated in metastatic nodules compared to the primary tumor tissues." (PMID 38997291, 2024). "Together, our data suggest that NF1, TSC1, or TβRII inactivation resulted in a tumor cell non-autonomous immune suppressive microenvironment that is potentially mediated by LAG3+ CD8 T and CD4 T cells." (PMID 38997291, 2024). "High pPAK1 was observed in NF1-mutant, SUZ12-mutant ST88-14 MPNST cells independent of CRISPRi suppression of NF2, suggesting PAK1 activation may be conserved across de-differentiated Schwann cell tumors after loss of either tumor suppressors or epigenetic regulators." (PMID 38216572, 2024). "BMDM cocultured with tumor cells induced both IL-1β expression and secretion; however, this effect was only observed using PDGFB mGBM tumors, but not Nf1-silenced mGBM cells." (PMID 37733448, 2023).
tumor (continued). "In the pacritinib-treated tumor, no changes in pMEK, total ERK, and BRAF were observed; however, pERK was downregulated and NF1 was significantly upregulated, likely reflecting pathway crosstalk." (PMID 35835937, 2022). "Lamotrigine treatment did not decrease optic nerve volumes (1.5-fold increased volumes relative to WT controls), unlike dark-reared Nf1-OPG mice or those genetically lacking Ngln322, where tumor initiation was completely prohibited." (PMID 35589737, 2022). "Interestingly, although the incomplete mutation of NF1 alleles is a driver of tumors, some researchers present a contradiction in that the absence of NF1 in T cells could increase T cell activity to enhance the physical immune monitoring mechanism of the tumor and inhibit malignant migration." (PMID 34663417, 2021). "Baseline MRI was originally not indicated for NF1-OPG screening, since the detection of an asymptomatic tumor rarely changes the management course." (PMID 33821340, 2021). "Other groups have found a reduction in expression of PTEN, a tumor suppressor in the PI3K/AKT/mTOR pathway, in MPNSTs compared to benign nerve sheath tumors in a manner that is not regulated by NF1." (PMID 32369930, 2020). "Despite the presence of both conditions there was not additive effect of NF1 and PKD2 in terms of the severity of tumour development and/or ADPKD progression." (PMID 32533764, 2020). "Despite the presence of both conditions there was not additive effect of NF1 and PKD2 in terms of the severity of tumor development and/or ADPKD progression." (PMID 32533764, 2020). "STX3451 induced apoptosis and disrupted both microtubule- and microfilament-based cytoskeletal structures in NF1 ST88 cells, but did not induce programmed cell death in the benign PNF tumour cells." (PMID 31730023, 2019). "For the tumor suppressors RB1, NF1, and SMAD4, the high-amplitude deletions (<−0.9) are not cleanly separated from the other bins by expression." (PMID 26787600, 2016). "Treatment of animals with MLN8237 resulted in stabilized disease for tumour explants from both patients, as opposed to the linear expansion of tumour volumes in the vehicle treated cohorts (SP-MPNST, p <0.0001; NF1-MPNST, p= 0.0011)." (PMID 23328114, 2013). "Although specific NF1-targeted systemic therapies for epithelial tumors are not yet established, pathway-directed agents (for example, MEK inhibitors) are an area of active investigation in NF1-related neoplasia." (PMID 41245174, 2025). "Median tumor volume at diagnosis accounted for 12.5 cm3 (0.04–68.5, n = 33), showing a higher median tumor volume in non-NF1 OPG as compared to NF-1 OPG, whereas no statistical significance could be shown (17.9 vs 4.9 cm3, p = 0.15)." (PMID 40643687, 2025). "While not definitive, our findings could suggest that her tumor possibly diverged phylogenetically to form these distinct subpopulations based on ERBB2 and NF1 copy number status." (PMID 39069534, 2024). "Based on these observations, we hypothesized supplementing stroma-derived factors, such as IL-1β, could restore PDGFB-driven (PN), but not Nf1-silenced (MES), tumor cell production of MCPs." (PMID 37733448, 2023). "Among the 3 tumors with weak-moderate expression of Pan-TRK, case #3 was diagnosed as NF1-related GIST in which NTRK1 break-apart was captured in only a few tumor cells (<15%) and could not be diagnosed as an NTRK1 rearrangement." (PMID 36612101, 2022). "Interestingly, the described cases of co-existing NF1, GH excess, and OPG to date had normal appearing pituitary glands on radiography, without evidence of tumor or hyperplasia." (PMID 35456261, 2022).
tumor (continued). "In the setting of NF1, inhibition of MAP-Kinase pathway with the so-called MEK inhibitors is a promising option of pharmacological intervention in cases a tumour reduction should be performed; however, it is surgically not possible or associated with too many risks." (PMID 32506255, 2020). "Similar to results in the NF1 MPNST mouse model, we did not observe tumor shrinkage in our trial." (PMID 31427883, 2019). "None of the 7 adult patients with NF-1 and PNF of PH underwent a successful tumor resection." (PMID 29849532, 2018).